NLRP3 (NLR family pyrin domain containing 3)
Diseases named in the same sentence as NLRP3 in open-access papers (continued):
Sharing a sentence is not in itself a finding about the gene and the disease.
neurodegenerative disease (continued). "In addition, donepezil, which indirectly activates α7nAChR, significantly reduced LPS-mediated NLRP3 inflammasome activation, a key factor in neuroinflammation and neurodegenerative disease, in this cell line." (PMID 34638977, 2021). "As a cytosolic multiprotein complex that participates in various inflammatory and neurodegenerative diseases, NLRP3 inflammasome could be activated by mtROS and thereby affected by the mitochondria-selective autophagy." (PMID 33717152, 2021). "In recent years, it has been demonstrated that NLRP3 inflammasome plays an important role in diverse neurodegenerative diseases; however, its implication in ALS remains unclear." (PMID 33802349, 2021). "The NLRP3 inflammasome is of particular interest in neurologic disorders because it can be activated by sterile cellular stressors common to many neurodegenerative diseases including proteinaceous insult, oxidative stress, environmental toxicants, and cell death." (PMID 32680528, 2020). "Despite the fact that inhibition of NLRP3 inflammasome activation has been shown exert beneficial effects in animal models of neurodegenerative diseases, the effectiveness and safety of specific NLRP3 inflammasome inhibitors in patients have yet to be verified in clinical trials." (PMID 32792920, 2020). "It is tempting to assume that the proposed link of the NLRP3 IL-1/IL-18 axis with this multitude of metabolic and degenerative diseases may hold therapeutic potential in treating these diseases, via NLRP3 inhibition." (PMID 32550001, 2020). "The NLRP3 inflammasome plays a vital role in the brain of patients with neurodegenerative disease." (PMID 33362467, 2020). "However, many important topics still need to be explored, such as how the activation or inhibition of the NLRP3 inflammasome influences neurodegenerative diseases." (PMID 32792920, 2020). "Increasing evidence indicates a link between NLRP3 and neurodegenerative diseases, although the exact roles and mechanisms by which the NLRP3 inflammasome regulates neurodegenerative diseases remain unclear and require further confirmation." (PMID 32792920, 2020). "The NLRP3 inflammasome affects the pathogenesis of the neurodegenerative disease." (PMID 33362467, 2020). "The CTSB release from LMP could lead to activation of NLRP3 inflammasome and NLRP3-dependent neuronal pyroptosis can result in neurodegenerative diseases such as AD." (PMID 30881285, 2019). "Emerging evidence showed that NLRP3 inflammasomes could be identified in microglia, astrocytes and neurons, which induced neuroinflammation in a series of neurodegenerative diseases." (PMID 30918581, 2019). "Besides, the activation of the NLRP3 inflammasome also serves as a vital factor for the onset and development of neurodegenerative diseases." (PMID 30233319, 2018). "Furthermore, considering the critical role of Nlrp3 inflammasome in the development of neurodegenerative diseases, our study also indicate that miR-30e induces neuron regeneration at least partially via inhibition Nlrp3 inflammasome-mediated inflammation." (PMID 29274035, 2018). "As a result, inhibiting the NLRP3 inflammasome may serve as a potential and effective therapeutic strategy in the treatment of neurodegenerative diseases." (PMID 30233319, 2018). "The role of the NLRP3 inflammasome in neurodegenerative diseases has recently been investigated." (PMID 29665808, 2018). "Thus, the inhibition of NLRP3 inflammasome is considered a therapeutic target of neurodegenerative diseases." (PMID 30107806, 2018). "In this review article, we briefly discuss the structure and activation the NLRP3 inflammasome and address the involvement of the NLRP3 inflammasome in several neurological disorders, such as brain infection, acute brain injury and neurodegenerative diseases." (PMID 28337127, 2017).
neurodegenerative disease (continued). "Our findings provide a direct link between NLRP3 inflammasome activation and PD pathogenesis, which will give us an insight into the potential of miR-7 and NLRP3 inflammasome in terms of opening up novel therapeutic avenues for neurodegenerative diseases including PD." (PMID 27084336, 2016). "In summary, when exposed to endogenous and exogenous stimuli, the NLRP3 inflammasome in microglia is activated, promoting the M1 phenotype and enhancing pyroptosis—a downstream event that leads to cell death and neuroinflammation, thus exacerbating the progression of neurodegenerative diseases." (PMID 39411285, 2024). "Therefore, emerging strategies for combating neurodegenerative diseases may include treatments that target both upstream and downstream pathways of the NLRP3 inflammasome." (PMID 39683782, 2024). "Targeting NLRP3 signaling pathway to inhibit brain inflammation could be effective for treating ADRD and neurodegenerative diseases Although some NLRP3 inhibitors have been tested in clinical trials for inflammatory diseases, none have been successful in treating ADRD." (PMID 39764140, 2024). "As we known, neuronal pyroptosis and neuroinflammation mediated by NLRP3 inflammasome play an important role in neurodegenerative diseases, which are important regulators of microglial neuroinflammation, we next sought to explore the effects of microglial NLRP3 on DA neurodegeneration." (PMID 36199191, 2022). "Given that mature IL-1β secretion has been shown to be a key mediator in inflammation-induced neuronal apoptosis in neurodegenerative disease, our mechanistic finding suggests that pharmacological inhibition of NLRP3 may alleviate inflammation through Caspase 1 dependent mature IL-1β secretion." (PMID 35431795, 2022). "In this review, we will summarize results implicating the inflammasome as a pivotal player in the pathogenesis of neurodegenerative diseases and discuss how compounds that hamper the activation of the NLRP3 inflammasome could offer novel therapeutic avenues for these diseases." (PMID 33670164, 2021). "Recent reports suggested that activation of TXNIP/NLRP3 axis was positively associated with pain and emotion disorders and the neuroprotective properties by pharmacological inhibition or genetic deletion of TXNIP following cerebrovascular and neurodegenerative diseases." (PMID 33898422, 2021). "As with many other neurodegenerative diseases, AD is also marked by a large inflammatory response and recent data are consistent with the hypothesis that Aβ-induced activation of the NLRP3 inflammasome enhances AD progression by mediating a harmful chronic inflammatory tissue response." (PMID 25158693, 2014). "In the context of neurodegenerative diseases, the most investigated inflammasome is the nucleotide-binding domain (NOD), leucine-rich repeat (LRR), and pyrin domain-containing protein-3 (NLRP3) inflammasome." (PMID 38791415, 2024). "Various inflammasomes play essential roles in neurodegenerative diseases, primarily the nucleotide-binding oligomerization domain (NOD)-, leucine-rich repeat (LRR)-, and pyrin domain (PYD)-containing protein 3 (NLRP3) inflammasome." (PMID 36757612, 2023). "Activation of CB2 receptor is reported to inhibit the activation of NLR Family Pyrin Domain Containing 3 (NLRP3) inflammasome, a potent contributor of neuroinflammation and neurodegenerative diseases." (PMID 38264546, 2023). "We here validate NOX4 as a key player in NLRP3 inflammasome activation, suggesting NOX4 pharmacological inhibition as a potent therapeutic approach in neurodegenerative diseases." (PMID 37760032, 2023). "Numerous evidences suggested that the activation of Nlrp3 plays a vital role in DCD and other neurodegenerative diseases." (PMID 35721719, 2022).
neurodegenerative disease (continued). "Therefore, the discovery of inhibitors of NLRP3 inflammasome activation from bioactive compounds derived from natural substances might be a promising future strategy for the prevention and treatment of neurodegenerative diseases." (PMID 33525754, 2021). "The focus of this study is on the NLRP1, NLRP3, and NLRC4 inflammasomes because they have garnered the most attention in the progression of neurodegenerative diseases." (PMID 31915018, 2020). "In addition, in this review article, we also focus on the therapeutic implications of targeting novel inhibitors of the NLRP3 inflammasome or of novel drugs that mediate the NLRP3 pathway, which could play a role via NLRP3 in the treatment of neurodegenerative diseases." (PMID 32792920, 2020). "Moreover, NLRP3 and the related molecules released following its activation may be useful as potential biomarkers of neuroinflammatory conditions and as predictive factor for other neurodegenerative diseases." (PMID 32867310, 2020). "Although the majority of studies on neurodegenerative diseases and NLRP3 inflammasome show that NLRP3 inhibition is beneficial for the regression of the disease symptoms, two studies at least suggest that outcomes of NLRP3 activation may have a protective role on the symptoms." (PMID 31892810, 2019). "Increasing evidence implicates the NLRP3 inflammasome and its activation/release products; ASC specks, caspase-1 and IL-1β in the pathogenesis of neurodegenerative disease and stroke." (PMID 29654318, 2018). "Finally, the most reported inflammasomes involved in the pathogenesis of neuroimmune and neurodegenerative diseases are NLRP3 and NLRP1; whether other inflammasomes are potential important factors contributing to these disorders is worth studying in the future." (PMID 29849483, 2018). "In addition to neurodegenerative diseases, inhibition of the cGAS/STING/NLRP3 signaling pathway can also improve neonatal hypoxic-ischemic encephalopathy and cerebral venous sinus thrombosis." (PMID 40463371, 2025). "Furthermore, NLRP3 inflammasome inhibitors like MCC950 have demonstrated promise in reducing neuroinflammation and improving outcomes in animal models of neurodegenerative diseases." (PMID 40558545, 2025). "In addition to NLRP3, other inflammasomes such as AIM2, NLRC4 and NLRP1 and their downstream effector molecules have been found to play pathological roles in neurodegenerative diseases." (PMID 39710713, 2024). "NLRP3 inflammasome activation, assembled by NLRP3-ASC-caspase-1, may drive neurodegenerative diseases." (PMID 37238000, 2023). "Hence, we here validate NOX4 as a key player in NLRP3 inflammasome activation, suggesting NOX4 pharmacological inhibition as a potent therapeutic approach in neurodegenerative diseases." (PMID 37760032, 2023). "NLRP3 inflammasome is not a member of the host immune system but induces metabolic, genetic, and degenerative diseases such as cancer." (PMID 30209319, 2018). "The results suggest that NLRP3 inhibitors such as MCC950 may be a promising therapeutic candidate for neuroinflammation and may provide new inspiration for the development of therapeutic approaches for the treatment of various neurodegenerative diseases." (PMID 41230093, 2025). "In addition to neurodegenerative diseases and cardiovascular diseases, the cGAS/STING/NLRP3 signaling pathway is involved in the pathological process of acute pancreatitis, mastitis, acute kidney injury, acute liver injury, acute lung injury, systemic lupus erythematosus, and allergic rhinitis." (PMID 40463371, 2025). "The role of NLRP3 in neurodegenerative diseases has not yet been extensively investigated." (PMID 31375685, 2019). "Taken together, our data suggests that NLRP3 inhibition alone may not be sufficient to address dynamic and complex neuroinflammatory pathobiological mechanisms including dysregulation of multiple inflammasome pathways in neurodegenerative disease such as ALS." (PMID 37575265, 2023).
neurodegenerative disease (continued). "The data discussed so far suggest that NLRP3 inflammasome and the molecules released following its activation may be considered as potential biomarkers to improve the early detection of TBI complications as well as the preclinical stage of different neurodegenerative diseases." (PMID 32867310, 2020). "Other NLRP3 inhibitors such as BOT-4-one and INF39 have not been tested in neurodegenerative disease models." (PMID 39710713, 2024). "We showed that SARS-CoV-2 promotes α-synuclein mediated NLRP3 inflammasome activation by priming MDMi through spike protein, providing ex vivo support for the negative impact of SARS-CoV-2 on neurodegenerative diseases such as PD." (PMID 36316366, 2023). "In cerebral ischemia and neurodegenerative diseases, cytosolic double-stranded DNA (dsDNA) activates the cyclic GMP-AMP synthase (cGAS) signaling pathway in microglia, promoting the expression of (Absent in melanoma 2) AIM-2/ NLRP3 and GSDMD, which leads to cell polarization and pyroptosis." (PMID 39994107, 2025).
cardiovascular diseases (252 papers, 2013 to 2026). "NLRP3, which has received the most study in cardiovascular disease, has been linked to increased IL-1β (IL1B) production and caspase-1 activity, as well as impaired cardiac function." (PMID 40332346, 2025). "In cardiovascular disease research, the NLRP3 inflammasome and associated pathways are central drivers of vascular pathologies, particularly in myocardial injury and cardiomyopathy." (PMID 40832584, 2025). "Many other cardiovascular disorders, like structural cardiomyopathy and idiopathic cardiomyopathy, are also linked to the NLRP3 inflammasome activation-mediated inflammatory pathway." (PMID 40643515, 2025). "The NLRP3 inflammasome, a key player in the inflammatory response linked to cardiovascular disease, presents a promising target for novel therapeutic approaches." (PMID 39022620, 2024). "In conclusion, cardiovascular system diseases are associated with the activation of NLRP3 inflammasome." (PMID 38317229, 2024). "In light of this research, NLRP3 inflammasome activation can be easily correlated with the risk of cardiovascular disease." (PMID 38945951, 2024). "Several other cardiovascular diseases, such as hereditary structural cardiomyopathy and idiopathic dilated cardiomyopathy, are also associated with NLRP3 inflammasome activation." (PMID 38317229, 2024). "Much epidemiological evidence suggests that inflammation mediated by inflammatory molecules, including the NLRP3 inflammasome, is a powerful risk factor for cardiovascular disease." (PMID 38317229, 2024). "It is reported that the activation of the NLRP3 inflammasome pathway in cardiac fibroblasts can cause Ang-II-induced cardiovascular diseases, including atrial arrhythmia." (PMID 39334820, 2024). "The NLRP3 inflammasome, a cytosolic complex found in pro-inflammatory immune cells, has been implicated in several cardiovascular diseases and is responsible for the processing and release of IL-1β using active caspase-1 (CASP1)." (PMID 39763850, 2024). "In experimental models of cardiovascular disease, studies indicate that Tet2-deficient macrophages promote disease via enhanced production of IL-1β through the NLRP3 inflammasome." (PMID 39742155, 2024). "The activation of NLRP3 mediates the occurrence of pyroptosis and is associated with the occurrence and development of various cardiovascular diseases." (PMID 38172692, 2024). "Acrolein, a common environmental pollutant, is linked with cardiovascular diseases, and exposure of HUVECs (human umbilical vein endothelial cells) to acrolein stimulates NLRP3 inflammasome assembly and pyroptosis via promoting ROS secretion in HUVECs." (PMID 37063905, 2023). "Cd (cadmium) is a crucial environmental pollutant associated with cardiovascular diseases, Cd-treated HUVECs increase ROS secretion and activate NLRP3 inflammasome, further strengthening pyroptosis of HUVECs." (PMID 37063905, 2023). "Among the various inflammasomes, the NLR family pyrin domain-containing 3 (NLRP3) inflammasome stands out as the most extensively studied regulator implicated in the pathogenesis of cardiovascular diseases (CVDs)." (PMID 37958528, 2023). "Our observations that IRE1 plays an upstream role in NLRP3 signaling are also in accordance with prior findings regarding the association of ER stress with cardiovascular disease." (PMID 35167493, 2022). "Both end products of the activation of NLRP3, the cytokines IL-1β and IL-18, are pro-inflammatory and have been associated with several acute and chronic inflammatory diseases, including cardiovascular diseases." (PMID 35204152, 2022). "The formation and activation of NLRP3 inflammasome in hematopoietic cells are implicated in cardiovascular diseases." (PMID 36252682, 2022). "NLRP3 inflammasome activation via DAMPs and oxidative stress has been implicated in increasing susceptibility to chronic inflammatory disorders, such as cardiovascular diseases." (PMID 35563697, 2022).